SFRP1 (secreted frizzled related protein 1)
Diseases named in the same sentence as SFRP1 in open-access papers (continued):
Sharing a sentence is not in itself a finding about the gene and the disease.
pancreatic cancer (continued). "SFRP1 promoter hypermethylation has previously been detected in tumor tissue, pancreatic juice and cell-free DNA from patients with pancreatic cancer." (PMID 29212200, 2017). "In summary, our study shows that the identified core CpG island CGI2 of SFRP1 might be a promising tool for the development of clinical assays in pancreatic cancer prognosis and treatment response prediction." (PMID 36765639, 2023). "In addition, we found strong DNA methylation changes in CGI2 compared to the surrounding CpGs underlining the potential impact of this identified core CpG island in regulating SFRP1 expression in pancreatic cancer." (PMID 36765639, 2023). "Hence, DNA methylation of SFRP1 in pancreatic cancer cells seems to be a prominent epigenetic modification." (PMID 36765639, 2023). "Therefore, this study was designed to identify crucial regions of SFRP1 CpG site hypermethylation and further evaluate their potential clinical impact in pancreatic cancer." (PMID 36765639, 2023). "SFRP1 promoter hypermethylation represents a potential biomarker that may help to stratify pancreatic cancer patients for chemotherapy response." (PMID 36765639, 2023). "By measuring DNA promoter hypermethylation in the plasma of patients with stage IV pancreatic cancer, it was recently shown that promoter DNA methylation of the tumor suppressor gene SFRP1 has a high value for predicting failure of drug treatment with gemcitabine." (PMID 36765639, 2023). "Even though we focused on CCDC80 in the present study, it would be worth investigating whether ITM2A and SFRP1 are involved in the action of combination treatment of vactosertib with nal-IRI/5-FU/LV in ameliorating pancreatic cancer." (PMID 32076068, 2020). "Upregulation of miR-940 suppresses GSK3β and sFRP1 and could promote pancreatic carcinoma proliferation and invasion." (PMID 32019170, 2020). "The experimental results showed that the mRNA expression levels of EMP1, GIPR, SFRP1, CXCL11 and COL17A were significantly high in the pancreatic cancer cell line compared with the controls." (PMID 37547756, 2023). "In pancreatic cancer, this is reflected by our finding of a strong inverse correlation between DNA methylation status of CGI2 and SFRP1 mRNA expression." (PMID 36765639, 2023). "Here, we demonstrate that SFRP1, a negative regulator of WNT signaling and a point of crosstalk between the two pathways, was upregulated in pancreatic tumors." (PMID 27750213, 2017). "We observed an inverse trend between mean CpG island 2 methylation status and SFRP1 mRNA expression, but the p-value was not significant in this small cohort of pancreatic cancer cell lines (n = 6, Spearman r = −0.7714, ns p = 0.1028)." (PMID 36765639, 2023). "Likewise, it decreased expression of another HH/GLI1 target gene, Secreted frizzled-related protein 1 (SFRP1), which was upregulated in pancreatic cancer." (PMID 27750213, 2017). "Interestingly, we found that the PANC-1 cell line, commonly used in pancreatic cancer research, does not show SFRP1 promoter methylation at CGI2." (PMID 36765639, 2023). "However, a detailed molecular analysis of the SFRP1 promoter region hypermethylated in pancreatic cancer has not been performed yet." (PMID 36765639, 2023). "After conducting a thorough analysis of published studies on cfDNA methylation in pancreatic cancer, as well as a comparative methylation analysis using the TCGA database, we have identified a set of consistently reported hypermethylated genes: BMP3, NPTX2, SFRP1, SPARC, and TFPI2." (PMID 37481552, 2023). "Interestingly in a single pancreatic cancer cell line (PANC-1), we found nearly no CGI2 methylation and concordantly abundant mRNA expression of SFRP1, which contrasts previous MSP studies." (PMID 36765639, 2023).
breast tumors (21 papers, 2007 to 2023). "Moreover, many breast tumors show hypermethylation of the secreted Frizzled-related protein 1 (sFRP1) promoter region, causing low expression of this WNT antagonist." (PMID 19473496, 2009). "Putatively, SFRP1 loss may be associated with nuclear β-catenin accumulation in human breast tumors." (PMID 19422694, 2009). "The finding that SFRP1 down-regulation promotes anoikis resistance, migration as well as invasion, and increases the population of CD44High/CD24low is quite significant because it may partially explain why breast tumors with lost SFRP1 expression are associated with poor patient prognosis." (PMID 19422694, 2009). "Some key genes are densely connected, such as FOXQ1 and SFRP1, which are well-known molecules driving the heterogeneity and progress of breast tumors." (PMID 27786176, 2016). "In primary breast tumours, methylation frequencies of SFRP1, SFRP2, SFRP5 and DKK1 were 40, 77, 71 and 19%, respectively." (PMID 18283316, 2008). "For example, expression of the extracellular inhibitor of WNT signaling, secreted Frizzled-related protein 1 (sFRP1), which competes with FZD receptors for ligand binding, is downregulated in many breast tumors and is associated with poor prognosis." (PMID 17897439, 2007). "We show that sFRP1 blocks proliferation of many breast tumor cell lines through interference with pathway activation that is presumably driven by endogenous WNT ligands." (PMID 17897439, 2007). "Interestingly, in the GENT2 platform, SFRP1 expression was higher in poorly differentiated breast tumors compared to moderately (log2 FC = 0.90; p-value < 0.05) and well-differentiated breast tumors (log2 FC = 2.49; p-value = 0.12)." (PMID 37190179, 2023). "This was supported by the finding that the extracellular inhibitor of Wnt/β-catenin pathway expression named secreted frizzled-related protein 1 (SFRP1) is significantly downregulated in many breast tumors and this is related to poor prognosis as well as therapy resistance." (PMID 35978075, 2022). "Consequently a high frequency of human breast tumors shows hypermethylation and transcriptionally silencing of the SFRP1 gene." (PMID 25036590, 2014). "Our data suggests that DNA methylation reflected by the CDH13, RASSF1A and SFRP1 locus panel might have a role in the phenotype of breast tumor subtypes." (PMID 22701537, 2012). "Since sFRP1 expression is lost in primary breast tumors and tumor cell lines by promoter hypermethylation, this might be one mechanism contributing to WNT pathway activity." (PMID 17897439, 2007). "This was corroborated by the TNMplot.com public dataset analyses, which demonstrated that SFRP1 expression was lower in tumoral breast tissue (fold change (FC) = 0.20) compared to normal breast tissue, and lower in metastatic (FC = 0.77) compared to breast tumors (Kruskal-Wallis p-value < 0.0001)." (PMID 37190179, 2023). "Additionally, aberrant activation of the WNT signaling pathway has been detected in breast tumors, and the expression of Frizzled-related protein 1 (sFRP1), a secreted factor that inhibits WNT signaling, is downregulated in many breast tumors and associated with poor prognosis." (PMID 27487128, 2016). "The majority of breast tumors exhibit evidence of activation of canonical Wnt/β-catenin signaling and alterations predicted to upregulate Wnt/β-catenin signaling have been reported, including epigenetic silencing of Wnt antagonists SFRP1 and WIF1 and upregulation of Wnt ligands and Fzd receptors." (PMID 20126544, 2010). "The decreased expression is consistent with previous studies showing downregulation of overall SFRP1 and SFRP2 expression in breast tumors through DNA promoter hypermethylation." (PMID 37091166, 2023). "A direct coherence of the identified BDNF/SFRP1 expression axis is further supported by the significant correlation of BDNF and SFRP1 protein expression in primary breast tumors." (PMID 25036590, 2014).
breast tumors (continued). "In the current study we tested the impact of ectopic sFRP1 expression in the aggressive, basal-like MDA-MB-231 breast tumor cells." (PMID 19473496, 2009). "To analyze the signaling pathways involved in the anti-proliferative activity of sFRP1, we examined its effects on canonical WNT signaling, which is constitutively active in most of the examined breast tumor cell lines." (PMID 17897439, 2007). "Five of the genes, all known tumor suppressor genes (RASSF1A, RARβ2, CDH13, HIN1 and SFRP1), were found to be frequently hypermethylated in breast tumor tissues but not in the adjacent non-cancerous tissues." (PMID 22701537, 2012). "We previously showed that when SFRP1 is knocked down in immortalized non-malignant mammary epithelial cells, the cells (TERT-siSFRP1) acquire characteristics associated with breast tumor initiating cells." (PMID 21303533, 2011). "Most breast tumors show hypermethylation of the promoter region of secreted Frizzled-related protein 1 (sFRP1), a negative WNT pathway regulator, leading to downregulation of its expression." (PMID 17897439, 2007). "SFRP1 expression was also higher in triple-negative compared to luminal (log2 FC = 3.14; p-value < 0.001) and HER2 (log2 FC = 2.99; p-value < 0.001) breast tumors and in basal compared to luminal (log2 FC = 2.96; p-value < 0.001) and HER2 (log2 FC = 2.82; p-value < 0.001) breast tumors." (PMID 37190179, 2023). "Furthermore, most breast tumors show hypermethylation of the promoter region of secreted Frizzled-related protein 1 (sFRP1) and low expression of this negative WNT pathway regulator." (PMID 19473496, 2009).
lung cancer (18 papers, 2010 to 2025). A malignant neoplasm involving the lung. "Dysregulation of canonical Wnt signaling has also been demonstrated in lung cancer, mediated through epigenetic silencing of negative regulators such as SFRP1 and WIF-1 or rare mutations in APC and β-catenin." (PMID 22016777, 2011). "Transcriptional silencing of SFRP1 by DNA methylation and loss of heterozygosity in lung cancer have been documented, supporting a role for this gene as a tumor suppressor, and SFRP1 hypermethylation was found to be associated with lymph node metastasis and progression." (PMID 21731750, 2011). "Studies indicate that upregulation of SFRP1 expression inhibits the Wnt/β-catenin pathway in nonsmall cell lung cancer and epithelial ovarian cancer." (PMID 38715918, 2024). "Another study found that miR-1254 targeted secreted frizzled related protein 1 (SFRP1), a Wnt/β-catenin pathway antagonist, to promote lung cancer cell proliferation." (PMID 33403035, 2021). "Clinical results confirm that concordantly low Rab37, low SFRP1, and high Oct4 stemness protein expression profile can be used as a biomarker to predict poor prognosis in lung cancer patients." (PMID 30158579, 2018). "Targeting Rab37-SFRP1-Wnt axis in select lung cancer patients with low Rab37 or low SFRP1 expression for SFRP1 protein treatment can be a potential strategy for development of personalized cancer treatment." (PMID 30158579, 2018). "Lung cancer patients with low Rab37, low SFRP1 protein expressions coincide with high Oct4 expression in their tumors." (PMID 30158579, 2018). "Taken together, our findings suggest that Rab37-mediated SFRP1 exocytic transportation exert inhibitory effects on lung cancer stemness." (PMID 30158579, 2018). "Our finding of Rab37-mediated exocytosis of SFRP1 in cancer cells provides a new insight into the role of Rab37 small GTPase in lung cancer stemness." (PMID 30158579, 2018). "It is possible that some lung cancer patients expressed low levels of SFRP1 through promoter hypermethylation." (PMID 30158579, 2018). "In conclusion, this study demonstrated that Rab37 mediates SFRP1 secretion to inactive the Wnt signaling pathway, and thus results in suppressing lung cancer stemness properties." (PMID 30158579, 2018). "Similarly, miR-1254 targets the Wnt/β-catenin pathway antagonist, secreted frizzled related protein 1 (SFRP1), and was upregulated in lung cancer tissues and cells promoting proliferation." (PMID 34001990, 2021). "Moreover, results of TCF/LEF reporter assay as well as IF and IHC of β-catenin localization confirmed that Rab37 regulated the exocytosis of SFRP1 to inhibit lung cancer stemness properties by attenuating the Wnt signaling components." (PMID 30158579, 2018). "In addition, quantitative analyses showed a positive correlation between Rab37 and SFRP1 in 68.8% of 109 lung cancer patients (P < 0.001)." (PMID 30158579, 2018). "Importantly, low expression of Rab37 or SFRP1 was associated with poor overall survival (OS) and progression-free survival (PFS) in lung cancer patients." (PMID 30158579, 2018). "Furthermore, we isolated Rab37-specific intracellular vesicles from PC-14 lung cancer cells by immunoprecipitation (IP) with Flag-tagged antibody followed by immunoblotting to detect SFRP1 protein level." (PMID 30158579, 2018). "Moreover, high expression of stem cell marker Oct4 coincided with low expression of Rab37 and SFRP1 in lung cancer patients with poor clinical outcomes." (PMID 30158579, 2018). "They suggested that SFRP1 is a candidate tumor suppressor gene for lung cancer." (PMID 29420609, 2018). "Interestingly, a direct link exists between the epigenetic inactivation of SFRP1 and the overexpression of microRNA (miR)-31, with exogenous overexpression of miR-31 leading to repression of SFRP1 in lung cancer cells." (PMID 24594839, 2014).
lung cancer (continued). "Since Rab37 overexpression inhibited lung cancer stemness properties and was inversely correlated with expression of Oct4 stemness gene in vitro and in vivo, we further analyzed the clinical manifestations in patients with low Rab37, low SFRP1 and high Oct4 expression." (PMID 30158579, 2018). "In a suggested mechanism, Rab37 mediates exocytosis of secreted frizzled related protein 1 (SFRP1), an antagonist of the WNT pathway, to suppress WNT signaling in lung cancer cells in vitro." (PMID 36317486, 2022). "Previous study has demonstrated that SFRP1 is a Wnt antagonist and acts as a tumor suppressor by repressing lung cancer stem-cell like traits, and DNMT3A correlates the epigenetic silencing of SFRP1 gene." (PMID 35860691, 2022). "In addition, overexpression of miR-31 in these cells depletes several other antagonists of Wnt signaling that have potential miR-31 binding motifs, including SFRP1, SFRP4, and WIF-1, which are often silenced in human lung cancer." (PMID 38309281, 2023). "The relationship between Rab37 and SFRP1 expression has never been examined in human cancer patients; we therefore performed IHC on surgical tumor specimens from 109 lung cancer patients." (PMID 30158579, 2018).
adenoma (16 papers, 2006 to 2024). A neoplasm arising from the epithelium. "Here, we report significantly increased hypermethylation frequencies for two secreted frizzled-related proteins, SFRP1 and SFRP2, in LS-associated adenomas and carcinomas when compared to normal colon." (PMID 26203307, 2015). "For SFRP1, significantly increased frequencies of hypermethylation were only observed in adenomas with high-grade dysplasia and carcinomas." (PMID 26203307, 2015). "The outcome of this, or whatever other mechanisms are involved, is that FAP adenomas show significant reductions in sFRP1 transcription compared with matched normal mucosa, despite their elevated β-catenin activity." (PMID 20628379, 2010). "Although sFRP1 gene hypermethylation is normally associated with complete silencing in sporadic adenomas, the lower levels of methylation observed in FAP adenomas appear to reflect partial suppression of gene expression." (PMID 20628379, 2010). "Analysis of the data using the Wilcoxon's signed-rank test shows that sFRP1 is significantly more methylated in adenoma compared with matched normal colonic mucosa in both FAP and sporadic patients." (PMID 20628379, 2010). "Adenomas from these patients had also been analysed for mRNA expression of β-catenin transcription target genes (sFRP1, NKD1 and c-myc) and the FZD3 receptor." (PMID 20628379, 2010). "In this study, we again found widespread phosphorylation (and nuclear localisation) of c-jun in FAP adenomas and in the cases that showed the highest levels of sFRP1 suppression." (PMID 20628379, 2010). "In those cases where β-catenin target genes were up-regulated, the degree of induction was comparable to that observed in sporadic adenomas, but the degree of sFRP1 suppression in FAP adenomas was smaller than in sporadic cases." (PMID 20628379, 2010). "In a second series of 11 adenomas, we identified methylation of the sFRP1 promotor region in all 11 samples, and this was increased compared with the surrounding normal mucosa in seven cases." (PMID 16523202, 2006). "sFRP1 mRNA expression was downregulated by more than 10-fold in all 12 adenomas compared with matched normal mucosa (median 485-fold, IQR 120- to 1500-fold)." (PMID 16523202, 2006). "This represented a reduction in sFRP1 protein expression in at least 45% of these benign adenomas compared with matched controls." (PMID 16523202, 2006). "In our adenoma series, however, sFRP1 mRNA levels were reduced by a median factor of 485-fold compared with matched normal mucosa." (PMID 16523202, 2006). "We have also complemented these data with immunohistochemical detection of the sFRP1 protein in a similar adenoma series." (PMID 16523202, 2006). "Immunohistochemical analysis using a polyclonal antibody supported these findings, with sFRP1 expression reduced in many of the adenoma samples examined." (PMID 16523202, 2006). "Immunohistochemistry with an antibody raised against sFRP1 detected a mostly cytoplasmic signal, which was reduced in adenomas." (PMID 16523202, 2006). "Another similarity with cancers was the common hypermethylation of the sFRP1 locus in adenomas and it is likely that this contributes to the reduction in transcription we observed." (PMID 16523202, 2006). "Decreasing protein levels of SFRP1 was also observed along the adenoma-carcinoma sequence." (PMID 26482433, 2015). "Significantly decreasing protein levels of SFRP1 could be observed along the adenoma-carcinoma sequence." (PMID 26482433, 2015). "Both the FAP and sporadic adenomas showed a similar trend of down-regulation of sFRP1 expression." (PMID 20628379, 2010). "In order to determine the level of sFRP1 transcription in early colorectal tumours, we performed quantitative analysis of sFRP1 mRNA levels, using real-time RT–PCR, in a cohort of 12 adenoma samples and compared these with expression levels in normal bowel mucosa sampled from the same patient." (PMID 16523202, 2006).